TNF (tumor necrosis factor)
Diseases named in the same sentence as TNF in open-access papers (continued):
Sharing a sentence is not in itself a finding about the gene and the disease.
colitis (continued). "It was observed that colitis did not interfere with the requirement of MPO activity and TNF-α levels, indicating that these inflammatory markers were not activated or deactivated and that other cytokines not investigated (IL-6 and IL-1β, e.g.)may be involved." (PMID 37577725, 2023). "TNFα is not significantly different between WT and Batf3-/- mice under HFD with acute DSS colitis." (PMID 35812447, 2022). "Consequently, we did not observe increased cell death after TNF stimulation of cells from patients with NDAS, and infection or colitis were not major clinical features." (PMID 35289316, 2022). "However, IL-1β, TNF-α, IgG, SOD, and MPO were not significantly affected by Gln, indicating that Gln is not so effective as Ala-Gln to suppress DSS-induced colitis." (PMID 34046146, 2021). "Moreover, tumor suppressor HACE1 deficient mice were also highly sensitive to DSS-induced experimental colitis, likely because lack of HACE1 in IECs led to reduction of TRAF2 ubiquitin and overactivation of TNF-α-induced necrosis, and subsequent inflammation." (PMID 34956195, 2021). "In addition to assessment of tissue monocytes, we found that murine blood monocytes produced heightened IL-1β, but not TNF, during DSS colitis." (PMID 30542349, 2018). "Other cytokines (TNF-α, IL-1β, IL-6, IL-23, and IL-12p70) were detected in low levels and were not significantly different between the rIL-33- and PBS-treated mice with DSS colitis (data not shown)." (PMID 26161006, 2015). "I3C did not alter TNF-α and IL-12 in male and female mice but increased the IL-1β and IL-6 in male mice and decreased IFN-γ in female and male mice, suggesting that I3C ameliorates colitis in females but not in males, indicating that I3C sex-specifically exhibits anti-colitis activity in mice." (PMID 40094833, 2025). "Furthermore, the effect of protective construction disappeared and the expression of colonic MPO, IL-1β, IL-6, or TNF-α at the protein level was not counteracted by BD in PGF mice, indicating that the gut microbiota was essential for the effect of BD during colitis." (PMID 40745657, 2025). "However, it was not enough to prevent or reverse the course of acute colitis induced by DSS, as observed by macroscopic (colon length reduction), biochemical (increased IL-1β, TNF-α, and CXCL2/MIP-2), and histopathological analyzes of colonic tissues performed at the end of the experiment." (PMID 37685250, 2023). "The mucosal expression of mRNA for TNF-α, IL-1β, iNOS, COX-2, SOD-1, SOD-2, GPx mRNAs, and the hypoxia inducible factor (HIF)-1α protein expression were upregulated in colonic mucosa of treadmill exercising HFD mice with colitis compared with those without exercise." (PMID 31117199, 2019). "Similar to the results of previous studies, digoxin efficiently attenuated the colitis induced by adoptive transfer of CD45RB+ CD4 T cells by downregulating Th17 cytokines and receptors, such as IL-17A, IFN-γ, and IL-23R, but did not influence mucosal TNF-α expression." (PMID 30804707, 2019). "TNFα is also an important pro-inflammatory cytokine, but we did not observe any increase in gene expression of TNFα by DSS in this study, indicating that DSS-induced colitis might not involve TFNα." (PMID 29890681, 2018). "Importantly, in mice pretreated with MKP-1 siRNA, Gln-mediated attenuation of colitis, i.e., DAI score, colon length, and histological inflammation, and score, and an increase in colonic levels of TNF-α and LTB4, were no longer observed." (PMID 29494494, 2018). "While the DCs subsets studied did not appear to significantly express TNF-α, there were significantly more numbers of MLN and PP CD8α+ DCs and only PP-derived CD8α- DCs that expressed IFN-γ from mice with live Mycobacteria-enhanced colitis, than compared to other groups." (PMID 18533024, 2008).
colitis (continued). "Furthermore, when TNFR2−/− mice are used in the colitis model, some studies have found that nTregs require TNFα via TNFR2 as a critical factor for optimizing Treg suppressive function under inflammatory conditions whereas iTregs are fully suppressive without TNF signaling." (PMID 29725328, 2018).
psoriasis (2,423 papers, 2005 to 2026). An autoimmune condition characterized by red, well-delineated plaques with silvery scales that are usually on the extensor surfaces and scalp. "TNFα inhibitors are associated with increased susceptibility to infections, paradoxical psoriasis, eczematoid lesions, and reactivation of tuberculosis." (PMID 41481132, 2026). "This study investigated genetic variants associated with psoriasis, psoriatic arthritis (PsA), and response to tumor necrosis factor alpha (TNF-α) inhibitors (adalimumab, infliximab, and etanercept) in a Russian cohort." (PMID 42196396, 2026). "TNF-α inhibitors are highly effective for psoriasis and PsA but are consistently associated with ANA seroconversion, anti-dsDNA induction, drug-induced lupus, and lupus flares." (PMID 41596733, 2026). "contains bioactive flavonoids and alkaloids that exert anti-inflammatory and antioxidant activities, and inhibit TNF-α, IL-1β, IL-6 and NF-κB signaling pathways implicated in the pathogenesis of psoriasis." (PMID 42306466, 2026). "In psoriasis, complications are more frequently associated with TNFα and IL-17 inhibition, including infections, paradoxical inflammation, and mucocutaneous candidiasis." (PMID 41481132, 2026). "This approach facilitates the dissection of molecular mechanisms underlying TNF-α blockade in epithelial cells, which are key contributors to the inflammatory milieu in psoriasis." (PMID 41155329, 2025). "Similar effects have been reported in other autoimmune diseases, such as psoriasis and inflammatory bowel disease, where TNF-α blockade was associated with reductions in somatic and psychiatric symptoms, including fatigue, depressive symptoms, and anxiety." (PMID 40943274, 2025). "This suppression reduces the production of key cytokines implicated in psoriasis, such as TNF-α, IL-17, IL-23, and IFN-γ, thereby attenuating keratinocyte hyperproliferation and immune cell infiltration." (PMID 40560394, 2025). "Novel biologics focus on psoriasis associated cytokines like TNF-α (e.g., adalimumab and infliximab) or the IL-23/IL-17 axis (e.g., secukinumab, ixekizumab)." (PMID 40995100, 2025). "Studies have revealed that some female patients treated with TNF-α monoclonal antibodies for inflammatory bowel disease developed psoriasis, with the underlying mechanism remaining obscure and warranting further investigation." (PMID 40303401, 2025). "The development of psoriasis involves numerous inflammation-related genes, including TNF (encoding tumor necrosis factor), CD4 (encoding the CD4 molecule), IL-10 (encoding Interleukin-10), and IL-4 (encoding Interleukin-4)." (PMID 40678620, 2025). "It has been shown that several cytokines were associated with psoriasis, including TNFα and IL-22, which both, either alone or in combination, promote IL-36 production by primary human keratinocytes and organotypic skin models." (PMID 40563994, 2025). "Network pharmacology analysis showed that 20 transdermal constituents were associated with potential therapeutic targets for psoriasis, including TNF, MMP9, TLR4, ICAM1, EGFR, and MAPK14." (PMID 41012530, 2025). "During a 10-year period, TNF inhibitor–treated patients had a reduced risk of developing any primary malignancy compared with biologic-naïve patients with psoriasis (hazard ratio [HR] = 0.80; 95% confidence interval [CI] = 0.73–0.87)." (PMID 40800120, 2025). "The increasing release of inflammatory cytokines, including IL-6, IL-17A, IL-22, IL-23, and TNF-a, by immune cells causes the worsening of epidermal symptoms and ultimately aggravating the psoriasis condition." (PMID 40807399, 2025). "Enrichment analysis of these genes revealed several signaling pathways implicated in psoriasis pathophysiology, including the TNF, and PI3K-Akt pathways." (PMID 40011539, 2025).
psoriasis (continued). "In this real-world cohort study, JAK inhibitor therapy was associated with a reduced risk of incident uveitis compared with TNF inhibitors among patients with ankylosing spondylitis, psoriasis, or psoriatic arthritis." (PMID 41208989, 2025). "Psoriasis-associated inflammatory cytokines (e.g., TNF-α, IL-17A, IL-23) and Th17 cells can compromise the blood-brain barrier (BBB)." (PMID 41357183, 2025). "In particular, TNF inhibitors demonstrated a reduced risk of hospitalization in patients with psoriasis." (PMID 40664730, 2025). "Among the therapies for psoriasis, ustekinumab has been frequently associated with biologic-induced BP, particularly in patients who have had unsuccessful anti-TNF-α treatment." (PMID 39859462, 2025). "Psoriasis is a chronic inflammatory autoimmune disease, a prototype TNFα–Th17 disease, which represents an individual risk factor for the development of cardiovascular diseases, significantly increasing the morbidity and mortality among affected patients." (PMID 40005022, 2025). "Nonetheless, there is insufficient empirical data directly linking these cytokine changes to TNF-α inhibitor-induced psoriasis, hindering the establishment of a definitive causal relationship." (PMID 40678000, 2025). "Observational studies report a 55% reduction in MI risk among TNF inhibitor-treated psoriasis patients compared to topical therapy cohorts." (PMID 40229608, 2025). "Inflammatory factors in psoriasis patients, such as TNF-α, IL-6, IL-22, etc., in addition to causing skin lesions, also promote the occurrence of metabolic disorders and increase the risk of MetS." (PMID 40385577, 2025). "Conversely, immunosuppressive treatments for psoriasis, such as TNF inhibitors, increase the risk of TB reactivation, highlighting the need for careful management in patients with both conditions." (PMID 40310305, 2025). "Psoriasis is caused by an imbalance of Th1/Th17 chemokines and cytokines such as IL-17, IL-23, TNFα, and IFN-γ, which can be explained as dysfunction of keratinocytes, immune cells, and inflammatory cells." (PMID 40906403, 2025). "The pro-inflammatory cytokines interleukin 23 (IL-23), IL-6, IL-1, and TNF-α are associated with the pathophysiology of psoriasis." (PMID 38712377, 2025). "Here, IFNγ and TNFα, the key Th1 cytokines implicated in psoriasis pathogenesis, induced SULT2B1 expression in human epidermal KCs, whereas Th2 and Th17 cytokines did not alter SULT2B1 expression." (PMID 41181147, 2025). "This keratinocyte SPRY1/CXCL10/periarticular CD14hi macrophage/TNF-α axis provides valuable insights into the mechanisms underlying the transition from psoriasis to PsA and suggests potential therapeutic targets for preventing this progression." (PMID 40471688, 2025). "Methotrexate and tumor necrosis factor‐alpha (TNF‐α) inhibitors represent well‐recognized agents associated with reduced cardiovascular risk in patients with psoriasis, PsA, and rheumatoid arthritis." (PMID 40916619, 2025). "Adalimumab, a monoclonal antibody that inhibits tumor necrosis factor alpha (TNF-α), is widely used in psoriasis therapy, yet its molecular effects on NF-κB-associated genes and microRNAs (miRNAs) in keratinocytes remain insufficiently defined." (PMID 41155329, 2025). "ANRIL was proven to be involved in the epigenetic regulation of genes related to inflammatory, apoptotic processes and TNF-α secretion; the association with certain SNPs points to the multifactorial landscape of psoriasis." (PMID 40725772, 2025). "Biologic-induced BP is a rare side effect of biologic treatments for psoriasis, typically associated with anti-TNF-α and anti-IL12/23 agents and rarely with guselkumab (anti-IL23)." (PMID 40422272, 2025). "A previous study conducted on Psoriasis patients from the European population reported that variants in the TNF -857C and TNFRSF1B 676T genes were associated with positive response when treated with Etanercept." (PMID 40469293, 2025).
psoriasis (continued). "Given that IL-23 and TNF-α are also implicated in the pathogenesis of psoriasis in murine models, we then examined the effect of IK14004 on production of these cytokines in PBMC cultures." (PMID 40868162, 2025). "The elevated expression of tumor necrosis factor-alpha (TNF-α) in psoriatic lesions is a key driver of the inflammatory process underlying psoriasis, as demonstrated by the effectiveness of TNF-α-targeted therapies." (PMID 40343299, 2025). "Further research is needed to fully elucidate these shared mechanisms, but the evidence so far underscores the importance of the TNF-IL-23-IL-17 axis in driving the inflammatory processes underlying psoriasis and autoimmune thyroid disorders." (PMID 40922376, 2025). "Psoriasis primarily involves the TNF-α and the IL23-Th17-IL17 pathway, while AD is associated with a Th2 response driven by IL-4 and IL-13." (PMID 39859462, 2025). "The activated immune cells produce large numbers of pro-inflammatory mediators, including IL-17, TNF-α, and IL-22, which in turn result in the activation of keratinocytes and form a positive feedback loop, eventually causing the expansion of psoriasis plaques." (PMID 40108109, 2025). "Psoriasis is associated with systemic inflammation characterized by elevated levels of pro-inflammatory cytokines such as TNF-α and IL-6, which not only contribute to skin pathology, but also interfere with metabolic processes." (PMID 40277935, 2025). "According to the immune mechanism underlying psoriasis, some biological agents targeting T-cell activation or cytokines, such as TNF, IL17, and IL23, are developed as therapeutics for psoriasis." (PMID 39959414, 2025). "The production of tumor necrosis factor-alpha (TNFα), interferon-gamma (IFNγ), and IL-8 is promoted around this IL-23/IL-17 A system, which is thought to cause a chain reaction of psoriasis exacerbations." (PMID 40481552, 2025). "Increased levels of IL-6, PAI-1, and TNF-α, commonly associated with visceral obesity, have also been found in psoriasis." (PMID 40909067, 2025). "According to recent data, TNF-α inhibitor therapy in psoriasis was associated with a significantly increased risk of overall cancer and lymphoma, while the risk of solid organ cancers was not elevated." (PMID 40649154, 2025). "The risk of MASLD in moderate-to-severe psoriasis is primarily linked to the inflammatory process, which induces pro-inflammatory cytokines such as interleukin (IL)-6, tumor necrosis factor (TNF)-α, and leptin." (PMID 40004904, 2025). "Several cytokines implicated in psoriasis pathogenesis, particularly interleukin-17 (IL-17) and tumor necrosis factor-alpha (TNF-α), are also known to contribute to hepatic inflammation and fibrogenesis." (PMID 40879966, 2025). "Lastly, TNF-α inhibitors are commonly implicated in drug-induced psoriasis, although through an unclear mechanism." (PMID 40606452, 2025). "TNF-α is instrumental in the IL-23/IL-17 axis, working in synergy with IL-17A to regulate cytokines and keratinocyte-associated genes involved in psoriasis." (PMID 40303401, 2025). "Th1 and Th17 cells play a key pathogenic role in psoriasis through the release of several cytokines including tumor necrosis factor alpha (TNF-α), and IL-17A, which, in turn, trigger the release of IL-6 and IL-1α by keratinocytes." (PMID 40046180, 2025). "These mice showed upregulated expression of IL-17 and TNF-α signaling-related cytokines and chemokines (e.g., TNF, Ccl20, Cxcl1, IL-22, IL-23a) and are more susceptible to psoriasis upon induction." (PMID 41583484, 2025). "Serum levels of CRP, VEGF, MMP-3, and ICAM-1 are strongly correlated with psoriasis-related scores, and some of these markers have been linked to clinical endpoints of anti-TNF therapy in RA studies." (PMID 40303401, 2025).
psoriasis (continued). "A number of proinflammatory cytokines involved in the pathogenesis of psoriasis, e.g., as tumor necrosis factor-alpha (TNF-α) and interleukin-17 (IL-17), have been implicated in the development of hepatic steatosis and inflammation." (PMID 40879966, 2025). "Psoriasis is typically linked to Th1 and Th17 cell-mediated inflammation, characterized by key cytokines such as TNF-α, IFN-γ, IL-12, IL-17, and IL-23." (PMID 40264783, 2025). "In the epidermis of a mouse model caused by IMQ or psoriasis patients, the expression of cytokines such as TNF-α, IL-23, IL-17, and IL-22 is very high." (PMID 40343294, 2025). "It is plausible that anti-TNF drugs are associated with an increased risk of infection in patients with psoriasis." (PMID 39065754, 2024). "It has been shown that TNF-α, an important pro-inflammatory cytokine implicated in the pathogenesis of psoriasis, enhances the initiation of autophagosome formation but impairs subsequent processing, which leads to a negative impact on autophagy." (PMID 38606161, 2024). "In this study, a retrospective analysis was conducted to investigate the incidence of ANA and APS-associated autoantibodies in psoriasis patients following treatment with TNF, IL-17, and IL-23 inhibitors." (PMID 38987260, 2024). "Similar to vitiligo, decreased levels of cathepsin D have been found in psoriasis and atopic dermatitis and have been linked to increased TNF-α levels." (PMID 38715599, 2024). "Pro-inflammatory cytokines such as tumor necrosis factor-alpha (TNF-α), interleukin 6 (IL-6), and interleukin 1 beta (IL-1β) are elevated in psoriasis and have been implicated in the pathophysiology of depression and anxiety." (PMID 39335361, 2024). "Among various diseases caused by TNFR1 and TNF-α, psoriasis and atopic dermatitis are representative inflammatory diseases developed on the skin." (PMID 38789573, 2024). "Compared with TNF-α inhibitors, the evidence of the HBVr risk in psoriasis patients receiving cytokine inhibitors (IL-12/23 inhibitor, IL-17 inhibitors, IL-23 inhibitor) was weak." (PMID 39861831, 2024). "ATP6V1G2 is situated in the HLA region, akin to the psoriasis susceptibility region containing HLA-C, such as TNF." (PMID 39026678, 2024). "The pathogenesis of psoriasis is complex and known pathogenic factors include TNF-α, IL-23, IL-17A, and so on." (PMID 38695018, 2024). "According to recent data, the overall incidence of paradoxical eczema following the use of biological drugs for psoriasis is low, with TNF inhibitors most frequently causing paradoxical eczema." (PMID 39768570, 2024). "The upregulation of several cytokines and kinases has been implicated in the pathogenesis of psoriasis, including tumor necrosis factor-α (TNF-α), IL-17A, IL-17F, and IL-23." (PMID 39459016, 2024). "The balance between Th17 and regulatory T-cells (Treg) is also altered in psoriasis, where Treg develop expression of RORγt and become functionally impaired; this can be partially explained by polymorphisms in genes such as TNF, IL12RB2, and IL12B." (PMID 38256115, 2024). "Increased levels of inflammatory cytokines such as TNF-α and IL-6 are associated with reduced sleep duration in psoriasis patients." (PMID 39188726, 2024). "Other than that, the SIRT1 activator SRT2104 exhibits promise in mitigating psoriasis symptoms by reducing the expression of genes linked to inflammatory responses and skin cell differentiation, which are IL-17 and TNF-α." (PMID 39456475, 2024). "Elevated levels of inflammatory cytokines such as TNF-α and IL-6 have been linked to reduced sleep in psoriasis." (PMID 39188726, 2024). "Univariate and multivariate logistic regression to identify associations between hs-CRP, IL-17, TNF-α, and atherosclerosis in psoriasis patients." (PMID 39104857, 2024). "Proposed treatments for patients with TNF inhibitor-induced psoriasis depend on the severity of the eruption, the underlying condition being treated, and the form of psoriasis eruption." (PMID 39781163, 2024).